MB (myoglobin)
Description:
Monomeric heme protein which primary function is to store oxygen and facilitate its diffusion within muscle tissues. Reversibly binds oxygen through a pentacoordinated heme iron and enables its timely and efficient release as needed during periods of heightened demand. Depending on the oxidative conditions of tissues and cells, and in addition to its ability to bind oxygen, it also has a nitrite reductase activity whereby it regulates the production of bioactive nitric oxide. Under stress conditions, like hypoxia and anoxia, it also protects cells against reactive oxygen species thanks to its pseudoperoxidase activity.
Synonyms: PVALB; MYOSB
Tractability: Small molecule: a structure with a bound ligand is known; a high-quality ligand is known. PROTAC: a small molecule that binds it is known.
Gene: Protein-coding gene on chromosome 22 (35,606,764 to 35,637,951, reverse strand). Ensembl gene ENSG00000198125.
Subcellular location: Cytoplasm, sarcoplasm
Pathways (Reactome):
Transport of small molecules: Intracellular oxygen transport
Gene Ontology:
Molecular function: nitrite reductase activity; oxygen carrier activity; peroxidase activity; protein binding; heme binding; oxygen binding
Biological process: removal of superoxide radicals; oxygen transport; skeletal muscle contraction
Cellular component: extracellular exosome; sarcoplasm; cytosol
Genetic constraint (gnomAD): Loss-of-function variants: 8 observed, 13.97 expected, observed/expected ratio (o/e) 0.57, 90% interval 0.34 to 1.03. The upper end of that interval is the gene's LOEUF score, 1.03, which puts it in group 4 of 6, group 1 being the genes least tolerant of losing a copy. Missense variants: 164 observed, 198.95 expected, observed/expected ratio (o/e) 0.82, 90% interval 0.73 to 0.94. Synonymous variants: 89 observed, 82.47 expected, observed/expected ratio (o/e) 1.08, 90% interval 0.91 to 1.29.
Homologues: Orthologues: chimpanzee MB (99% identical), macaque MB (90% identical), guinea pig MB (89% identical), mouse Mb (84% identical), rat Mb (83% identical), dog MB (66% identical), rabbit MB (64% identical), zebrafish mb (40% identical), Drosophila melanogaster glob1 (21% identical), Caenorhabditis elegans glb-34 (17% identical), Caenorhabditis elegans glb-14 (16% identical). Paralogues in human: CYGB (30% identical), HBZ (25% identical), HBA1 (24% identical), HBA2 (24% identical), HBD (23% identical), HBG1 (23% identical), HBG2 (23% identical), HBB (23% identical), HBE1 (22% identical), HBM (22% identical), HBQ1 (21% identical).
Diseases named in the same sentence as MB in open-access papers:
MB is named in the same sentence as 268 diseases in open-access papers, as found by Europe PMC text mining. Sharing a sentence is not in itself a finding about the gene and the disease. The quoted sentences say what the papers report.
rhabdomyolysis (224 papers, 2005 to 2026). Necrosis or disintegration of skeletal muscle often followed by myoglobinuria. "Other risk factors for AKI in pediatric rhabdomyolysis include higher peak CK levels, higher serum or urine myoglobin levels, metabolic acidosis or lower bicarbonate levels, abnormal urinalysis findings, and lower serum calcium levels." (PMID 40310119, 2025). "Muscle injury due to prolonged ischemia leads to rhabdomyolysis, causing the release of multiple substances such as myoglobin, iron, and free radicals." (PMID 40291968, 2025). "Bile casts (due to hyperbilirubinemia) or myoglobin casts (due to rhabdomyolysis) can obstruct renal tubules, causing cast nephropathy and oliguria." (PMID 40111731, 2025). "This is related to the mechanism of AKI caused by rhabdomyolysis, where myoglobin is a key driving factor." (PMID 40055771, 2025). "Exposure to heat stress, causes rhabdomyolysis that releases myoglobin into the bloodstream, which is then filtered by the kidneys." (PMID 41141547, 2025). "In our study, CK levels higher than 25 812 IU/L were associated with severe AKI, which shows the importance of myoglobin in rhabdomyolysis-induced AKI." (PMID 39869334, 2025). "Further research is needed to better delineate the clinical spectrum of RYR toxicity and to develop evidence-based strategies for myoglobin clearance and organ protection in rhabdomyolysis-associated AKI." (PMID 40909457, 2025). "Based on symptoms, and elevated levels of myoglobin and creatine kinase, the patient was diagnosed with rhabdomyolysis, acute renal failure and toxic encephalopathy caused by diquat poisoning." (PMID 39991050, 2025). "In aggregate, these observations support the consideration of CS hemoadsorption in the management of severe rhabdomyolysis, particularly in patients with very high myoglobin levels (>10,000 μg/L) who are at imminent risk or already have evidence of AKI." (PMID 41398626, 2025). "The pathogenesis of rhabdomyolysis-induced AKI is associated with the myoglobin released from the muscle." (PMID 38282162, 2024). "The pathogenesis of AKI in rhabdomyolysis is multifactorial and related to myoglobin intratubular precipitation but also to inflammatory causes with mediators effectively removed by adsorption columns." (PMID 39223785, 2024). "CO poisoning can cause rhabdomyolysis and acute renal failure, as an effect and as a consequence of direct toxic damage to the skeletal muscle and the ability of CO to bind myoglobin." (PMID 38730995, 2024). "Since myoglobin seems to be the main cause of kidney damage in rhabdomyolysis, one therapeutic approach is extracorporeal removal from the bloodstream." (PMID 38907120, 2024). "The progression of rhabdomyolysis-induced AKI is believed to be associated with the generation of oxygen-free radicals that originate from myoglobin." (PMID 38911241, 2024). "Considering the levels of creatine phosphate kinase and myoglobin, the diagnosis or exclusion of rhabdomyolysis caused by Botrychium ternatum intoxication should be made, and suitable treatment should be administered accordingly." (PMID 38428852, 2024). "Increased levels of myoglobin can cause up to 40% of patients with rhabdomyolysis to develop acute renal failure." (PMID 39759753, 2024). "Released myoglobin plays a fundamental role in the pathogenesis of rhabdomyolysis-associated AKI by increasing oxidative stress, inflammation, endothelial dysfunction, vasoconstriction, and cell injury." (PMID 38994971, 2024). "Rhabdomyolysis is a clinical syndrome caused by the rapid disruptions of skeletal muscle and the release of myoglobin (Mb) and other intracellular components into blood circulation." (PMID 38256961, 2024). "The potential for the adsorption of both myoglobin and cytokines offers the possibility of targeting two well-described contributors to the underlying pathophysiology of rhabdomyolysis and associated AKI." (PMID 39085790, 2024).
rhabdomyolysis (continued). "Our case further implicates antimalarial therapy as a cause of rhabdomyolysis and increases awareness of myoglobin cast nephropathy as a potential complication of malaria." (PMID 38375068, 2024). "Among the complications associated with rhabdomyolysis, prerenal azotemia and the nephrotoxicity of free myoglobin can precipitate acute kidney injury (AKI), further exacerbating metabolic abnormalities." (PMID 39105028, 2024). "Myoglobin is the pathogenic factor in rhabdomyolysis-induced AKI, but it is rarely directly measured in serum and urine." (PMID 38256366, 2024). "The pathogenesis of rhabdomyolysis induced-AKI has been linked to the production of oxygen free radicals derived from myoglobin." (PMID 38629092, 2024). "Consensus Statement 1: Myoglobin contributes to the development of AKI through both direct and indirect mechanisms with raised myoglobin and CK levels associated with the risk of developing rhabdomyolysis (Strong consensus: Q: 1,2)." (PMID 39085790, 2024). "The release of myoglobin into the bloodstream in the context of rhabdomyolysis is one of the main factors causing renal dysfunction." (PMID 37575481, 2023). "The causative role of myoglobin toxicity in AKI is more certain in cases with severe rhabdomyolysis (creatinine kinase > 15,000 IU/L), which rarely occurs in patients with TBI." (PMID 37661277, 2023). "Due to the nephrotoxic properties of myoglobin compounded by the frequent occurrence of rhabdomyolysis in clinical settings associated with renal hypoperfusion, one plausible explanation is the combined effect of hemodynamic and toxic insults to the kidney." (PMID 37344851, 2023). "Its action on muscle cells and red blood cells causes rhabdomyolysis and intravascular hemolysis, which results in the release of myoglobin and free hemoglobin." (PMID 38376456, 2023). "Myoglobin is said to be the main culprit of renal injury due to rhabdomyolysis, as it is excreted by the kidneys causing urine to be stained red or brown." (PMID 35409969, 2022). "Lastly, trauma and stress-related muscle exhaustion are the main causes of rhabdomyolysis, which entails a massive release of myoglobin in the blood." (PMID 36552389, 2022). "Such color changes of renal medulla are a conventional characteristic of glycerol-induced rhabdomyolysis associated with the accumulation of myoglobin in the kidney tissue." (PMID 36293129, 2022). "The heme component of myoglobin plays a crucial role in the pathogenesis of rhabdomyolysis-associated acute kidney injury (RM-AKI)." (PMID 35294485, 2022). "While CK is widely used for laboratory diagnosis of rhabdomyolysis, kidney injury is believed to be caused by myoglobin, which peaks and drops much faster than CK." (PMID 33575135, 2021). "Exertional rhabdomyolysis, a condition associated with both heavy exercise and kidney injury as a result of excessive myoglobin release into the bloodstream, has been described primarily in ultra-endurance runners." (PMID 34863204, 2021). "Mechanical ventilation and severity of the rhabdomyolysis, including myoglobin level, are associated with the risk of stage 2–3 AKI." (PMID 32124091, 2020). "The patient was diagnosed with rhabdomyolysis associated with fenofibrate monotherapy as confirmed by symptoms of fatigue and muscle pain, and elevated levels of myoglobin and creatine kinase." (PMID 32481339, 2020). "It is well known that damage of skeletal muscle can cause release of myoglobin, initiating the pathophysiologic process associated with rhabdomyolysis." (PMID 31964405, 2020). "One precisely defined cause of AKI is rhabdomyolysis, characterized by damage of skeletal muscles and the leakage of muscle cell contents into the circulation, e.g., myoglobin and other proteins." (PMID 33176824, 2020).
rhabdomyolysis (continued). "A widely used animal model of such AKI is the rhabdomyolysis model, in which the damage is caused by the release of thigh muscle heme, mainly from myoglobin, into the circulation and subsequent accumulation in different tissues." (PMID 29471681, 2019). "The pathophysiology of rhabdomyolysis-induced AKI was believed to be triggered by myoglobin as the toxin causing renal dysfunction." (PMID 30135658, 2018). "The main cause of rhabdomyolysis, the extreme breakdown of muscle fibers, and release of myoglobin into the bloodstream in fact can be caused by many factors." (PMID 26693360, 2015). "One patient with a Ccr of 19.6 ml/min had a CK value exceeding the maximum (>23,000 U/L) and ​​myoglobin value (>1000 U/L), and the renal injury was considered to be associated with rhabdomyolysis." (PMID 24236203, 2013). "Although only low myotoxicity activity was reported in experimental studies with LV, the venom clearly caused rhabdomyolysis in the current experiment, as evidenced by significant CK increase and deposition of myoglobin in renal tissue." (PMID 21655312, 2011). "Rhabdomyolysis is defined as muscle symptoms associated with a CK level elevation greater than 10 times the upper limit of normal and is usually associated with brown urine and the presence of myoglobin in urine; on the basis of these criteria, the patient was diagnosed with rhabdomyolysis." (PMID 40635153, 2025). "Current prevention strategies for rhabdomyolysis-associated AKI emphasize early recognition of high-risk patients (e.g. myoglobin >10,000 μg/L), aggressive yet judicious fluid resuscitation, hemodynamic optimization, avoidance of nephrotoxins, and close laboratory monitoring." (PMID 41398626, 2025). "Of note, most of rhabdomyolysis-associated tubular damage could be ascribed to myoglobin reabsorption through the endocytic receptor megalin located at the luminal cell surface." (PMID 39085790, 2024). "In addition to impaired renal function and inflammation, oxidative stress has been linked to the development of myoglobin-induced renal injury in rhabdomyolysis-associated AKI." (PMID 36795689, 2023). "Laboratory findings in autoimmune rhabdomyolysis will demonstrate an elevation of creatine kinase as well as elevations in aldolase, myoglobin, lactate dehydrogenase, aspartate aminotransferase, and alanine aminotransferaseas can be seen in other causes of rhabdomyolysis." (PMID 37170192, 2023). "Three predictors were used for matching: SAPS II as a predictor for the severity of the disease, patients’ age as a predictor to estimate the recovery from the underlying disease, and myoglobin as a predictor for the severity of rhabdomyolysis and renal toxicity." (PMID 37728069, 2023). "Myoglobin-associated rhabdomyolysis and renal toxicity should be considered in patients with TBI." (PMID 37661277, 2023). "The biopsy showed acute tubular injury with myoglobin casts (rhabdomyolysis-associated) and diffuse tubular degenerative and regenerative changes, mild interstitial fibrosis, and superimposed C3 mesangial deposits suggestive of resolving infection-related glomerulonephritis." (PMID 37963892, 2023). "It is well known that glycerol-associated rhabdomyolysis is accompanied by a release of myoglobin into the bloodstream followed by its oxidation and a release of iron ions, which could activate the Fenton reaction and lipid peroxidation in the kidneys." (PMID 36293129, 2022). "Admission myoglobin provides information to assess the risk for developing severe rhabdomyolysis following crush injuries and may help decide to start (or not) early preventive actions, such as intensive hydration, to decrease AKI risk." (PMID 34559325, 2021). "Rhabdomyolysis is a syndrome caused by injury to skeletal muscle and involves leakage of large quantities of potentially toxic intracellular contents into the plasma, such as myoglobin." (PMID 34857045, 2021).
rhabdomyolysis (continued). "Risk factors for AKI in the presence of rhabdomyolysis include hyperkalemia, hyperphosphatemia, hypocalcemia, dehydration, acidosis, sepsis, intravascular volume depletion, high serum myoglobin concentrations and low myoglobin clearance." (PMID 32998294, 2020). "The clinical aspects, the increased activity of serum enzymes indicative of muscular damage, the presence of myoglobin in urine were clear diagnostic indicators of severe rhabdomyolysis, and the gross and histological findings confirmed a myopathy associated with renal damage in one case." (PMID 33105842, 2020). "Here, we investigated the potential in vivo protective effects of the two rA1M-variants in a mild variant of the glycerol-induced rhabdomyolysis mouse model where AKI develops as a result of muscle rupture with release of myoglobin, heme, radicals, and other tissue components." (PMID 29471681, 2019). "Free heme, a pro-oxidant released from myoglobin, is thought to contribute to the pathogenesis of rhabdomyolysis-associated acute kidney injury (RM-AKI), because renal overexpression of heme oxygenase-1 (HO-1), the rate-limiting enzyme in heme catabolism, confers protection against RM-AKI." (PMID 28704479, 2017). "AKI induced by rhabdomyolysis is mainly caused by disrupted muscle cells that release myoglobin." (PMID 28018795, 2016). "Although the exact mechanism by which rhabdomyolysis causes renal failure is unknown, renal vasoconstriction/hypoperfusion, renal tubular obstruction secondary to cast formation, and myoglobin-mediated tubular cytotoxicity are the proposed mechanisms." (PMID 25371840, 2014). "Furthermore, CK is generally considered the best overall parameter to determine the risk for development of its main complication AKI, whereas myoglobin is actually the main causative protein for developing AKI-associated rhabdomyolysis." (PMID 23497406, 2013). "Although myoglobin is thought as the single most important cause of rhabdomyolysis-induced AKI, only studies with small sample sizes are available to explore this hypothesis." (PMID 23497406, 2013). "The pathophysiology of rhabdomyolysis-induced AKI is believed to be triggered predominantly by myoglobin, which may cause renal dysfunction by direct renal cytotoxicity after reaching the tubules, vasoconstriction and tubular obstruction." (PMID 23497406, 2013). "Because it also has extrarenal elimination kinetics, our data suggest that measuring myoglobin in patients at risk for rhabdomyolysis in the ICU may be useful." (PMID 23497406, 2013). "We have previously presented the results of myoglobin clearances in three critically ill patients with rhabdomyolysis treated with continuous hemodiafiltration, which was associated with a mean daily myoglobin removal of 1.8 g/day with a myoglobin clearance of 4.6 ml/min." (PMID 15774055, 2005). "Because myoglobin is eliminated quickly and elimination occurs outside of the renal system, our data indicate that routinely measuring myoglobin on admission and, subsequently, in patients at risk of developing rhabdomyolysis in the ICU setting might be of clinical value." (PMID 23497406, 2013). "Laboratory tests showed severe hypokalemia (1.5 mmol/L), metabolic alkalosis, and markedly elevated creatine kinase and myoglobin levels, consistent with rhabdomyolysis." (PMID 42063617, 2026). "A different application is in the case of rhabdomyolysis: This condition leads to the massive release of myoglobin, which can result in acute kidney injury." (PMID 40724567, 2025). "In the absence of the possibility to integrate biomarkers in everyday practice, we consider the continuous monitoring of myoglobin, CK, electrolytes, and acid–base status to be essential in patients with rhabdomyolysis." (PMID 39797358, 2025). "In the setting of rhabdomyolysis, studies have shown that convective therapy is more effective at removing middle and large molecules such as myoglobin when compared to diffusive therapy." (PMID 39375217, 2025).